CD80 (CD80 molecule)
Diseases named in the same sentence as CD80 in open-access papers (continued):
Sharing a sentence is not in itself a finding about the gene and the disease.
melanoma (continued). "All the canonical DC maturation-associated markers evaluated—MHC-I, MHC-II, and CD80—showed a higher percentage of positive cells in TRIMEL-stimulated cells when compared with control cells stimulated with the lysate generated with nontreated (no-HS) melanoma cells." (PMID 29744371, 2018). "Mature DCs induce co-stimulation through CD40, CD80, CD86 and OX40L while they circulate in peripheral sites regulating innate and adaptive anti-melanoma immunity." (PMID 29285320, 2017). "Immature DCs efficiently phagocytosed melanoma Apo-Nec cells and matured after phagocytosis as evidenced by increased expression of CD83, CD80, CD86, HLA class I and II, and 75.2 ± 16% reduction in Dextran-FITC endocytosis." (PMID 18221542, 2008). "Taken together, our findings indicate that the enrichment of mesenchymal cancer cells and the change in the IC ligand repertoire towards CD80/CD155 expression act as predictive biomarkers of anti-PD-1/PD-L1 response in cSCC, HNSCC, and melanoma patient samples." (PMID 38914547, 2024). "However, IRF7 knockdown with small interfering RNA (siRNA) significantly inhibited these inflammatory factors (IL‐1β, TNF‐α, IFN‐α, and IFN‐β), CD80 and CD86 in macrophages co‐cultured with irradiated melanoma cells." (PMID 38286661, 2024). "It is possible to speculate that overexpression of antigen presentation molecules (e.g. MHC-I and II) and co-stimulatory molecules (e.g. CD80 and CD86) can enhance anti-tumour immune response in the melanoma model." (PMID 38668817, 2024). "CD25-Foxp3+CD4 Tregs significantly increased in melanoma TILs and decreased in dLNs after treatment with anti-PD-1 but not anti-CD80 mAbs, implying PD-1 blockade prevented CD25−Foxp3+CD4 egress from tumor to dLNs." (PMID 35449134, 2022). "Moreover, nanocomplex increased the infiltration of NK cells and T cells in tumors prominently as well as the expression of CD80 on DCs, which inhibited the growth of murine B16F10 melanoma." (PMID 35745800, 2022). "The expression of CD80, normally found on dendritic cells or macrophages, was increased in MDSCs in patients with malignant melanoma, and it was also up-regulated on MDSCs in a murine ovarian cancer model; its ligation of CTLA-4 through CD80 on Tregs is crucial for T cell suppression." (PMID 35628647, 2022). "We next investigated whether CD40, CD80, and ICOS-L expression correlates with the outcome and therapeutic response in melanoma patients." (PMID 34092233, 2021). "The induction of CD40, as well as CD80 and ICOS-L, in RGS-treated melanoma tumors, may form a positive feedback loop to further sensitize tumors to RGS treatment." (PMID 34092233, 2021). "By querying The Cancer Genome Atlas (TCGA, N = 480) patient datasets of melanoma samples, we found that the CD40 expression was significantly correlated with CD80 (Spearman p < 0.0001, r = 0.6456) and ICOS-L (Spearman p < 0.0001, r = 0.5209) in tumors from melanoma patients." (PMID 34092233, 2021). "Therefore, we examined the correlation between IL-32 gene expression and the DC marker CD11c (also known as ITGAX) as well as the costimulatory molecules CD40, CD80, and CD86 in melanoma samples from The Cancer Genome Atlas (TCGA)." (PMID 32841222, 2020). "We showed that treatment with melanoma-derived exosomes or miR-125b-5p overexpression induced a morphological switch of M1 macrophages together with an enforced expression of IL-1β, CCL-1, CCL2, and CD80 (B7-1)." (PMID 32079286, 2020). "We investigated whether the use of a MART-1 expressing chimeric Ad5/3, targeting CD80 and CD86 on DCs, could result in efficient priming and activation of melanoma specific CD8+ T effector cells both in vitro and in a human ex vivo SLN model." (PMID 30022005, 2018). "By contrast, blockade of MAPK inhibits the negative effect of melanoma cells on the CD80, CD83 and CD86 expression thus restoring the DC co-stimulation." (PMID 29285320, 2017).
melanoma (continued). "Previously we reported that in vitro treatment with GGTI-298 induces a dose-dependent increase in the membrane expression of CD80 and CD86 costimulatory molecules in the murine melanoma cells B16F10 and an increase in CD86 in two human melanoma cell lines, including LB1319-MEL." (PMID 20140259, 2010). "Therefore, we aimed to determine the expression levels of CD80, CD86, and PD -L1 in malignant melanoma tissue samples by immunohistochemistry and to investigate the possible relationship between these proteins and the clinicopathological features in this study." (PMID 37614091, 2024). "Conversely, non-responder and relapsed tumors exhibited increased percentages of Vim+, CD80+, and CD155+ cancer cells, indicating that cancer cell features might affect the efficacy of anti-PD-1/PD-L1 therapy in cSCC, HNSCC, and melanoma patients." (PMID 38914547, 2024). "In addition, CD80 expression was significantly higher in cells stimulated with TRIMEL when compared with primary AM cells stimulated with nontreated melanoma cell-derived lysates." (PMID 29744371, 2018). "Furthermore, CD80, CD83, and CD86 expression on DC was decreased upon co-culture with melanoma cells and could be partially restored with BRAF inhibition in BRAFV600E mutant melanoma cell lines." (PMID 24194739, 2013). "DC co-cultured with melanoma cells alone did not present significant phenotypic characteristics of DC maturation (CD80: ~5%, CD83: ~6%, CD86: ~10%), and co-culture with UV-irradiated apoptotic cells led to a non-significant increase of CD83 markers only (~11%)." (PMID 22029859, 2011). "In addition, analysis of E-cadherin, Vimentin, CD80, and CD155 proteins in cSCC patient samples shows their value as predictive biomarkers of anti-PD-1/PD-L1 response, which has also been corroborated in head and neck squamous cell carcinoma (HNSCC) and melanoma patient samples." (PMID 38914547, 2024). "In contrast, B7-1 (CD80) is not constitutively expressed in melanoma cells, but its ectopic expression increases melanoma immunogenicity." (PMID 40647495, 2025). "They revealed that both melanoma-negative and positive SLN LCs expressed lower levels of CD83, CD80, CD86, and HLA-DR (maturation markers) compared to epidermal explant–migrated (mature) LCs." (PMID 38791968, 2024). "In support of these reports, publications indicate that CD80 and CD86 expression in melanoma patients does not effect the prognosis." (PMID 37614091, 2024). "Their low expression of antigen presentation related genes (CD80 and CD274) and the absence of T cells at the earliest stage of melanoma regression support a T-cell independent action of macrophages on tumor cells." (PMID 37526660, 2023). "In contrast, CD80 and ICOSL are not correlated to the sensitivity of melanoma cells to the BRAF inhibitors." (PMID 34092233, 2021). "The immune and inflammatory response node contained 99 proteins and genes directly involved in the immune response such as interleukins and chemokines; T lymphocyte markers such as CD96, TLR8, CD80; or CCR5, beta-2-microglobulin (B2M) or absent in melanoma 2 (AIM2)." (PMID 37686682, 2023). "Given the lack of CD40 costimulatory molecule expression by melanomas, the ligation of CD86 or CD80 with T cell CD28 molecules may be even more critical." (PMID 35162988, 2022). "The data showed that injection of B16 melanoma cells could significantly increase the expression of CD86, but not CD80, on infiltrating NK cells (from 2.5% to 18.6%)." (PMID 24349559, 2013).
breast carcinoma (49 papers, 2003 to 2026). "In summary, our results showed that CD80 expression was associated with the malignancy of breast cancer." (PMID 35814211, 2022). "We found the CD80 expression was associated with the higher malignant pathological type of breast cancer." (PMID 35814211, 2022). "We revealed the associations of CD80 and the main molecular and clinical characteristics of breast cancer." (PMID 35814211, 2022). "Despite multiple studies supporting that CD80 plays a critical role in regulating adaptive and innate immunity during tumor progression, the role of CD80 and its association with the tumor immune microenvironment in breast cancer remains largely unknown." (PMID 35814211, 2022). "Lastly, monocytes isolated from individuals with early-stage breast cancer show decreased expression of key markers, including intercellular adhesion molecule 1 (ICAM-1; encoded by ICAM1), CD80 & CD86, and lower levels of TNF-α." (PMID 41550427, 2025). "Breast cancer cells utilize CTLA-4 to physically remove CD80/CD86 from antigen-presenting cells via force-mediated trans-endocytosis." (PMID 41550427, 2025). "CD80 is expressed in a variety of blood tumors and solid tumors, such as Hodgkin lymphoma, non-Hodgkin lymphoma, pancreatic cancer, breast cancer, lung cancer, etc." (PMID 39575257, 2024). "This work suggests a tailored immunotherapeutic strategy to regulate TAM-mediated immune reactions in breast cancer subtypes by epigenetically adjusting the expression of CD80 and MSLN by modifying MALAT-1 and HOTAIR." (PMID 38511067, 2024). "For example, the high expression of CD80 on the cell surface of lung adenocarcinoma significantly improved the overall survival of patients, while in breast cancer and squamous cell carcinoma of the skin, CD80 overexpression was an indicator of poor prognosis." (PMID 39575257, 2024). "To explore the expression pattern of CD80 in breast cancer, we further analyzed the large-scale transcriptome data on breast cancer from TCGA and METABRIC databases." (PMID 35814211, 2022). "In summary, these results further confirmed the important role of CD80 in the breast cancer immune microenvironment." (PMID 35814211, 2022). "Our results indicated that CD80 was positively correlated with the most relevant immune responses and negatively correlated with few immune responses in breast cancer." (PMID 35814211, 2022). "In this study, we aimed to investigate the role of CD80 both clinically and molecularly in breast cancer at a transcriptome level." (PMID 35814211, 2022). "In the present study, we analyzed the CD80 expression pattern in breast cancer via a total of 2994 breast cancer samples." (PMID 35814211, 2022). "In the past few decades, most of the studies have been focused on the role of PD1/PDL1 and CTLA-4 in breast cancer, while few studies paid attention to the potential role of CD80." (PMID 35814211, 2022). "In another phase I study, an HLA-A2+-matched allogeneic MDA-MB-231 breast cancer cell line was transfected with the costimulatory molecule B7-1 (CD80) and used as a vaccine against stage IV BC." (PMID 33466691, 2021). "Tan IIA was shown to inhibit breast cancer BT-20 cells by inhibiting the expression of PD-L1, cytotoxic T-lymphocyte-associated antigen 4 (CTLA-4), cluster of differentiation 80 [B7-1 (CD80)], and B7-2 (CD86)." (PMID 32265690, 2020). "Of note, we observed an association of the CD80/FOXP3 mRNA ratio with poor OS and DFS in breast cancer patients." (PMID 32601304, 2020). "In fact, we show here that up-regulation of the mRNA expression levels of PD-L1, FOXP3, CD80, CD40, and CD14 in PBMCs is associated with breast cancer." (PMID 26942414, 2017). "In conclusion, our data showed that the mRNA expression levels of PD-L1, FOXP3, CD80, CD40, and CD14 in PBMCs were associated with breast cancer burden." (PMID 26942414, 2017). "In breast cancer, CD80 and tumor cell efficacy in chemotherapy are strongly correlated." (PMID 39720726, 2024).
breast carcinoma (continued). "Our findings further suggest that CD80 might be a promising target for immunotherapy in breast cancer; future studies are warranted to elaborate on the potential co-regulatory role of CD80 and other immune checkpoint members." (PMID 35814211, 2022). "Furthermore, The Human Protein Atlas was used in our study to evaluate the immunohistochemistry (IHC) data pertaining to the protein expression of CD80 in breast cancer and normal tissue." (PMID 35814211, 2022). "Moreover, we observed that the association between the CD80 expression and immune and inflammatory responses is similar to the pattern of PD1 in breast cancer." (PMID 35814211, 2022). "Taken together, the CD80 expression was closely correlated with tumor malignancy in breast cancer." (PMID 35814211, 2022). "Despite the critical role of CD80 in the regulation of immune responses, the expression and biological functions of CD80 in breast cancer remain unknown." (PMID 35814211, 2022). "In summary, the CD80 expression was closely correlated with the malignancy of breast cancer, and our findings suggest that CD80 might be a promising target for immunotherapeutic strategies." (PMID 35814211, 2022). "In breast cancer, CD80 may lead to the progression and metastasis of breast cancer by regulating the innate immune system." (PMID 34852825, 2021). "Moreover, conditioned media from GRP78-silenced breast cancer cells increased macrophage CD80+ expression (an M1-like macrophage marker) while control transfected ZR-75-1 conditioned media showed elevated macrophage CD206+ an M2-like macrophage marker) cells." (PMID 29113324, 2017). "In this breast cancer-focused review, we explore the interactions between autophagy and two clinically relevant immune checkpoint pathways; the programmed cell death-1 receptor with its ligand (PD-L1)/PD-1 and the cytotoxic T-lymphocyte-associated protein 4 (CTLA-4)/CD80 and CD86 (B7-1 and B7-2)." (PMID 36295867, 2022). "In our study, it was shown that the low-risk patients had significantly higher levels of PD-1, PD-L1, PD-L2, CD80, CD86, and CTLA-4 than the high-risk patients, suggesting this low-risk subpopulation of breast cancer patients might benefit more from immune checkpoint blockade therapy." (PMID 36936274, 2022). "Silencing LDHC significantly downregulated the mRNA expression of PD-L1, CD80 and GAL-9 in MDA-MB-468 breast cancer cells." (PMID 40108668, 2025). "An increased B cell activation (CD19+ MHC-II+ CD80/CD86+), as well as an increased antibody titer against the cancer cells, was observed in breast cancer tumor models." (PMID 35110563, 2022). "A previous study reported that the CD80 expression was higher in MDA-MB-468, MCF-7, and MDA-MB-231 breast cancer cells than in normal MCF10A cells." (PMID 35814211, 2022). "Furthermore, we further analysis the correlation of risk score and immune checkpoint in breast cancer and demonstrated that most of key checkpoint were significantly differentially expressed between the two groups in breast cancer patients, including CD44, TIGIT, CTLA4, CD274, CD86 and CD80." (PMID 35052427, 2021). "that NDV infected MCF-7 cells have beneficial effects on the antigen presentation capacity of breast cancer patient derived dendritic cells demonstrated by an upregulation of CD40, CD80, CD83, CD86 and MHC class II (HLA-DR)." (PMID 34777344, 2021). "Here demonstrated the contribution of other checkpoint molecules such as CD80 suggest that studies on the combinatory application of these protein inhibitors might be of great importance, especially considering different features of only seemingly the same types of breast cancers." (PMID 34440813, 2021). "Mature DC membrane markers were analyzed by flow cytometry, and Mo-DCs obtained from breast cancer patients showed less HLA-DR, CD11c CD86, CD80, and CCR7 expressions when compared to Mo-DCs from healthy donors." (PMID 31827382, 2019).
breast carcinoma (continued). "This study showed that LPS-stimulated human dendritic cells (DCs) decreased the expression of HLA-DR, CD83 and costimulatory molecules (CD40, CD80 and CD86) following coculturing with CTLA-4+ breast cancer cells." (PMID 28099147, 2017). "constructed a novel breast cancer vaccine that co-expressed MUC1 and CD80." (PMID 39575257, 2024). "M1 markers (CD80 and CD86) showed a better correlation with markers of endothelial activation compared with total macrophage marker (CD68) and with M2 markers (CD163 and CD206) in breast cancer samples." (PMID 36248978, 2022). "We also showed by multiplex analysis that mRNA expression levels of compiled CD80/CD86, known receptors of CTLA-4, and PD-L1/PD-L2, known receptors of PD-1, demonstrated improved overall survival of patients with breast cancer, including all subtypes combined and with triple negative breast cancer." (PMID 35339889, 2022). "In addition, breast cancer and sepsis HLA-DRlow/- monocytes, when compared to HLA-DR++ monocytes, displayed significantly reduced levels of the co-receptors CD86, CD80 and the suggested anti-inflammatory monocyte-macrophage marker CD163." (PMID 25992611, 2015). "Likewise, epigenetic silencing of CD70, a CD80 related co-stimulatory molecule, by DNA methylation was noted during breast cancer progression in an in vitro model." (PMID 27377375, 2016). "Therefore, we analyzed the presence of CD14+HLA-DRlow/-Co-receptorlow/- (i.e. negative for co-receptors such as CD86 and CD80) Mo-MDSCs in the peripheral blood of breast cancer patients." (PMID 25992611, 2015).